CTSS (cathepsin S)
Diseases named in the same sentence as CTSS in open-access papers (continued):
Sharing a sentence is not in itself a finding about the gene and the disease.
tuberculosis (5 papers, 2016 to 2025). A chronic, recurrent infection caused by the bacterium Mycobacterium tuberculosis. "Based on KEGG pathway database, CTSS is involved in 4 different pathways (lysosome, phagosome, antigen processing and presentation, and tuberculosis)." (PMID 27014637, 2016). "Additionally, CTSS was involved in the disease pathway “Tuberculosis” and programmed cell death pathway “Apoptosis”." (PMID 38668343, 2024). "The second network was tuberculosis (P = 1.03E−03), including ATP6V1H, cathelicidin 1 (CATHL1A), CTSS, ITGB2, myeloid differentiation primary response protein MyD88 (MYD88), and RAB5A." (PMID 30514405, 2018).
aortic aneurysm (4 papers, 2016 to 2025). A ruptured aneurysm located in the wall of the proximal portion of the descending aorta proceeding from the arch of the aorta. "Eli Lilly’s non-covalent inhibitor LY3000328 reduced plasma CTSS activity in phase I and advanced to phase II for aortic aneurysm; its derivatives also demonstrate immunomodulatory effects in bladder cancer by regulating T-cell activity." (PMID 40692794, 2025).
astrocytoma (4 papers, 2016 to 2021). "Previous studies showed that CTSS was highly expressed in the human astrocytoma and glioblastoma tumor." (PMID 33613746, 2021).
colitis (4 papers, 2012 to 2024). Inflammation of the colon. "When administered into the colonic lumen of wild-type mice to replicate the increased luminal cathepsin S detected in mice with colitis, cathepsin S causes visceral pain." (PMID 24860547, 2014). "This approach has been used to detect activated cathepsin S in macrophages of tumors and the inflamed colon, as well as in spinal microglial cells during colitis." (PMID 24860547, 2014).
Crohn disease (4 papers, 2013 to 2025). A gastrointestinal disorder characterized by chronic inflammation involving all layers of the intestinal wall, noncaseating granulomas affecting the intestinal wall and regional lymph nodes, and transmural fibrosis. "By contrast, in supernatants prepared from fecal samples, cathepsin S activity was significantly increased in patients with ulcerative colitis (UC), and total cathepsin was increased in both UC and Crohn’s disease samples compared to those from healthy volunteers." (PMID 41436824, 2025). "The expression levels of four genes identified by microarray screening (PLCB2, HVCN1, CTSS, and DEF8) and one purine/thiopurine related gene (NME6) correlated significantly with the clinical activity of Crohn’s disease." (PMID 23437289, 2013). "Five genes (NME6 from the purine/thiopurine network, PLCB2 of the RAC1 network, and HVCN1, CTSS, and DEF8) correlated with the Harvey-Bradshaw index of Crohn’s disease activity." (PMID 23437289, 2013).
cystic fibrosis (4 papers, 2021 to 2026). Autosomal recessive disorder caused by pathogenic variants in the CFTR gene (cystic fibrosis transmembrane conductance regulator), which encodes a chloride and bicarbonate channel expressed in epithelial cells, and follow the diagnosis criteria. "CTSB, CTSL, and CTSS are overexpressed in lung tissues of patients with cystic fibrosis." (PMID 39559762, 2024). "Other cysteine proteases such as cathepsin S, B or L have been associated with cystic fibrosis and bronchiectasis severity in CF; however, no data have been published so far in patients with non-CF bronchiectasis." (PMID 34206113, 2021).
Hyperglycemia (4 papers, 2023 to 2025). An increased concentration of glucose in the blood. "Conversely, CTSS knockdown mitigates hyperglycemia-induced carotid restenosis, confirming immune cell-mediated CTSS involvement in microvascular complications." (PMID 40692794, 2025). "In summary, CTSS emerges as a critical molecular link between hyperglycemia and complications, positioning it as a promising target for both hyperglycemia prevention and complication management." (PMID 40692794, 2025). "More research is needed to understand the pathophysiological role of CTSS in hyperglycemia, but the findings of the current study provide strong evidence that CTSS plays a role in hyperglycemia-induced inflammation, angiogenesis, and vasculogenesis." (PMID 36982499, 2023). "Since HUVECs are a promising candidate for the in vitro study of hyperglycemia-induced vascular complications, we investigated the effects of a CTSS knockout in HUVECs in a hyperglycemic environment." (PMID 36982499, 2023). "It has been demonstrated that cathepsin S (CTSS) is activated in hyperglycemia and is involved in inducing the release of inflammatory cytokines." (PMID 36982499, 2023). "Hyperglycemia also directly upregulates CTSS in endothelial cells." (PMID 40692794, 2025). "CTSS inhibition could alleviate hyperglycemia-induced endothelial inflammation in vitro, and reduce hepatic glucose production in murine models, while maintaining unaltered glucose metabolism in skeletal myotubes and adipocytes." (PMID 40692794, 2025). "The findings of this study may shed light on the importance of CTSS silencing in hyperglycemia and establish effective guidelines for the development of novel therapeutics to treat hyperglycemic-related vascular complications." (PMID 36982499, 2023). "However, few studies have observed the relationship between silencing CTSS and vascular complications under hyperglycemia." (PMID 36982499, 2023).
leukemia (4 papers, 2016 to 2025). A malignant (clonal) hematologic disorder, involving hematopoietic stem cells and characterized by the presence of primitive or atypical myeloid or lymphoid cells in the bone marrow and the blood. "Furthermore, we focused on cathepsins (CTSs) expressed in the EV-associated leukemia cells for their novel biological functions in secretory vesicles." (PMID 41227296, 2025). "In this context, in order to confirm CTSs identification and functional characteristics for each leukemia cell line, we performed Western blot analysis both on whole lysates and EVs." (PMID 41227296, 2025).
liver diseases (4 papers, 2020 to 2023). "In the contest of liver disease, CTSS has been related to the regulation of different aspects of natural killer T (NKT) cell activation, and their inhibition prevent hepatic NKT cell expansion after lipopolysaccharides (LPS)-induced inflammation." (PMID 36674470, 2023).
myocardial infarction (4 papers, 2017 to 2022). Gross necrosis of the myocardium, as a result of interruption of the blood supply to the area, as in coronary thrombosis. "We have previously reported that the decrease in canstatin expression in the infarcted area after myocardial infarction in rats was caused possibly by cathepsin S." (PMID 32947968, 2020). "In this study, H&E stained slides and fibronectin, CD59, cathepsin S, troponin T, desmin, and myoglobulin stained immunohistochemistry slides of 20 cases diagnosed with early myocardial infarction were retrospectively analyzed." (PMID 35371665, 2022). "In vitro studies showed an increase in cathepsin S expression in cardiomyocytes one to three days after myocardial infarction." (PMID 35371665, 2022). "In another study, cathepsin S level was found to be high in blood in myocardial infarction." (PMID 35371665, 2022). "CTSS also regulates ECM degradation and mediates fibroblast transdifferentiation, thereby preserving left ventricular function after myocardial infarction." (PMID 33781257, 2021).
neuropathy (4 papers, 2021 to 2025). A disorder affecting the nervous system that manifests with pain, tingling, numbness, and/or muscle weakness. "The human ortholog of this gene (CTSS) encodes cathepsin S and is implicated in neuropathy." (PMID 39424970, 2024). "Our finding supported that CTSS inhibition results in an anti-inflammatory response in oxaliplatin-induced neuropathy, through the upregulation of IL-10." (PMID 33754020, 2021). "The pivotal role of CTSS in oxaliplatin-induced neuropathy was further validated in the Ctss-/- knockout mouse model." (PMID 33754020, 2021). "We demonstrated, using this animal model, that CTSS inhibition could protect animals from oxaliplatin-induced neuropathy, which was supported by the results from mouse behavioral tests, EM studies of sciatic nerves, and quantification of IENF density." (PMID 33754020, 2021).
pancreatitis (4 papers, 2020 to 2023). Inflammation of the pancreas. "In vivo experiments have also demonstrated that the high levels of fatty acids induced by hyperlipidaemia exacerbate the development of pancreatitis, and that cathepsin S inhibitors significantly alleviate hyperlipidemic pancreatitis." (PMID 35183119, 2022). "In this study, we investigated the role of CTSS in FFA-stimulated macrophage-induced pancreatic acinar cell pyroptosis in hyperlipidemic pancreatitis (HP)." (PMID 35183119, 2022). "Cathepsins, including cathepsin S, also mediate pancreatitis." (PMID 34572924, 2021). "Therefore, cathepsin S may be a new target for the clinical treatment of hyperlipidemic pancreatitis." (PMID 35183119, 2022). "CTSB, CTSL, and CTSS are known to be up-regulated in pancreatitis, and although the roles of CTSB and CTSL are well-established that of CTSS is less known." (PMID 35183119, 2022).
sarcoidosis (4 papers, 2020 to 2025). Sarcoidosis is a multisystemic disorder of unknown cause characterized by the formation of immune granulomas in involved organs. "quantified serum level cathepsin S for eighty nine healthy donors and one hundred and seven sarcoidosis patients using enzyme-linked immunosorbent test, revealing that CTSS may serve as a novel serum indicator for sarcoidosis, which was derived from transcriptomic profiling of alveolar macrophages." (PMID 39364409, 2024). "Similar to NL and NXG, sarcoidosis lesional macrophages upregulated expression of the macrophage polarization marker genes MARCO, FCGR3A, NR1H3; the ECM-encoding gene FN1; the protease-encoding gene CTSS; and genes associated with inflammation, S100A8 and CHI3L1." (PMID 39989459, 2025).
acute kidney injury (3 papers, 2022 to 2025). Sudden and sustained deterioration of the kidney function characterized by decreased glomerular filtration rate, increased serum creatinine or oliguria. "Further analyses that included vancomycin as an additional potential stressor revealed a common match for genes encoding cathepsin A, cathepsin C, cathepsin D and cathepsin S and an association of cathepsins with the lysosomal pathway, kidney disease and acute kidney injury." (PMID 35516525, 2022).
aneurysm (3 papers, 2019 to 2024). Bulging or ballooning in an area of an artery secondary to arterial wall weakening. "The hallmark of aneurysm pathology is an imbalance between CTSs and their endogenous inhibitors in the vascular wall, which causes extensive ECM degradation and progressive weakening of the aortic wall." (PMID 37202785, 2023). "In human and animal aneurysm lesions, CTSs (CTSB, K, L, and S) are highly expressed, whereas cystatin C is lacking." (PMID 37202785, 2023). "An example is from the cathepsin-S (CTSS) gene, which encodes a protease associated with vascular inflammation, atherosclerotic plaque rupture, and aneurysm." (PMID 30729177, 2019). "In addition, the altered levels of CTSs and their endogenous inhibitors in patients with ACVD, aneurysm, obesity, diabetes mellitus, and peripheral arterial disease indicate that these molecules can also serve as diagnostic biomarkers of ACVDs." (PMID 37202785, 2023).
cerebral infarction (3 papers, 2018 to 2022). An ischemic condition of the brain, producing a persistent focal neurological deficit in the area of distribution of the cerebral arteries. "Conversely, in the first week after cerebral infarction, the cathepsin S and the cathepsin S/cystatin C ratios are significantly elevated." (PMID 35453881, 2022).
co-infection (3 papers, 2020 to 2021). "Here we found that the PI saquinavir, contrary to ritonavir, is able to induce an increase of endolysosomal proteases activity especially of cathepsin S in Mtb infected macrophages and during co-infection with HIV." (PMID 33841429, 2021).
colorectal tumor (3 papers, 2016 to 2023). "The role of CTSS in colorectal tumors has been well elucidated in patients, with high expression indicating poorer prognosis." (PMID 27097645, 2016). "Whilst biologic based approaches to target CTSS have been substantially less investigated, encouraging findings have been generated, as exemplified by the monoclonal antibody Fsn0503, which was capable of attenuating invasion and angiogenesis within colorectal tumour models." (PMID 38116078, 2023).
dacryoadenitis (3 papers, 2017 to 2025). Inflammation and enlargement of the lacrimal gland. "In desiccation syndrome, CTSS/FKN signaling drives dacryoadenitis by recruiting T cells and macrophages into lacrimal gland—blocked by CTSS or FKN inhibition." (PMID 40692794, 2025). "The activity of the lysosomal enzyme CTSS is elevated in tears and lacrimal glands of male NOD mice with established dacryoadenitis compared to healthy BALB/c mice." (PMID 28348600, 2017).
glomerulosclerosis (3 papers, 2021 to 2025). A hardening of the kidney glomerulus caused by scarring of the blood vessels. "Selective CTSS inhibition in preclinical models reduces albuminuria, glomerulosclerosis, inflammation, and fibrotic remodeling." (PMID 41282674, 2025). "In db/db mice, proteinuria, glomerulosclerosis, and renal inflammation were alleviated by treatment with RO5461111, a selective CTSS activity inhibitor, and PAR2 inhibition was effective in attenuating glomerulosclerosis." (PMID 34663802, 2021).
inflammatory bowel disease (3 papers, 2018 to 2025). A spectrum of small and large bowel inflammatory diseases of unknown etiology. "Cathepsin S is a cysteine protease that has been implicated in inflammatory bowel diseases (IBD) for its ability to promote visceral pain." (PMID 41436824, 2025).
influenza (3 papers, 2009 to 2026). An acute viral infection of the respiratory tract, occurring in isolated cases, in epidemics, or in pandemics; it is caused by serologically different strains of viruses (influenzaviruses) designated A, B, and C, has a 3-day incubation period, and usually lasts for 3 to 10 days. "Given the contribution of cytokine storm to severe influenza outcomes, our findings position CTSS as a host-derived pathogenic mediator integrating viral and cytokine-driven injury pathways." (PMID 41258714, 2026). "Similarly, TUNEL assay confirmed that CTSS knockdown significantly reduced TUNEL-positive cells caused by influenza infection." (PMID 41258714, 2026). "Here, we identified cathepsin S (CTSS), a lysosomal cysteine protease, as a key mediator of influenza-induced lung injury." (PMID 41258714, 2026). "Targeting CTSS holds promise as a host-directed therapeutic approach to improve clinical outcomes in severe influenza, warranting further investigation and development." (PMID 41258714, 2026). "This study aimed to investigate the role of CTSS in the pathogenesis of influenza infection, with a particular focus on acute lung injury." (PMID 41258714, 2026). "Collectively, these data indicate that lowering CTSS activity helps preserve epithelial barrier integrity and intercellular junctions during influenza infection." (PMID 41258714, 2026). "This study identifies cathepsin S (CTSS) as a central driver of influenza-induced epithelial injury, acting downstream of viral replication and cytokine signaling to promote apoptosis, inflammation, and barrier disruption." (PMID 41258714, 2026). "To determine the role of CTSS in influenza infection-induced lung lesions, we first determined the expression and activity of CTSS in influenza virus-infected human lung epithelial (A549) cells." (PMID 41258714, 2026). "Among the most differentially expressed genes, myeloid cell nuclear differentiation antigen (MNDA) and cathepsin S (CTSS) were strongly upregulated in CD14+ monocytes after influenza vaccination." (PMID 34695164, 2021). "To determine whether CTSS—a lysosome-resident cathepsin markedly upregulated after influenza infection—undergoes subcellular redistribution, we examined subcellular CTSS distribution and activity over time." (PMID 41258714, 2026). "Therefore, we explored the mechanism of CTSS in influenza infection." (PMID 41258714, 2026). "Conversely, treatment with recombinant CTSS protein exacerbated IAV-induced PARP1 cleavage and cytokine expression in A549 cells, indicating that CTSS acts as an amplifier of influenza-induced inflammatory and pathological injury process." (PMID 41258714, 2026). "Moreover, treatment with recombinant CTSS protein enhanced influenza-induced PARP1 cleavage in a dose-dependent manner, further supporting a pro-apoptotic role for CTSS during infection." (PMID 41258714, 2026). "CTSW is known to facilitate influenza virus release from late endosome, although CTSS is an interferon-stimulated gene upregulated by IFN-γ, its role in influenza-induced tissue injury had not been elucidated." (PMID 41258714, 2026).
interstitial lung disease (3 papers, 2022 to 2025). A diverse group of lung diseases that affect the lung parenchyma. "Clinically, serum CTSS levels serve as biomarkers for interstitial lung disease and uveitis, while preclinical studies validate its therapeutic targeting in multi-organ pathologies affecting pulmonary, hepatic, cardiovascular, and neural systems." (PMID 40692794, 2025).
lysosomal storage disorders (3 papers, 2015 to 2025). "This review aimed to highlight the involvement of CTSs in inherited lysosomal storage disorders, with a primary focus to the emerging evidence on the role of CTSs in the pathophysiology of Mucopolysaccharidoses (MPSs)." (PMID 32326609, 2020).
metabolic syndrome (3 papers, 2021 to 2022). A cluster of metabolic risk factors for CARDIOVASCULAR DISEASES and TYPE 2 DIABETES MELLITUS. "Moreover, CTSS levels were higher in a population of T2D patients that had cardiovascular disease compared to T2D patients that did not have cardiovascular disease and the plasma CTSS levels were positively associated to components of the metabolic syndrome in obese adults." (PMID 36289617, 2022). "However, there is not much information regarding the role of CTSS and CTSL in NAFLD/NASH and in metabolic syndrome development or progression and thus further research should be conducted in this area." (PMID 36289617, 2022).
Nephropathy (3 papers, 2021 to 2025). A nonspecific term referring to disease or damage of the kidneys. "In addition, the upregulation of CTSS was detected in ochratoxin A-induced nephropathy, indicating that the findings of this study agree with previous work, suggesting that the high CTSS expression in IMN may be of great significance." (PMID 34819020, 2021). "Taken with our results, this suggests a local upregulation of CTSS expression (which may be driven by insulin resistance) occurs in the glomeruli and tubules in DKD which may contribute towards kidney damage." (PMID 39562547, 2024).
non-Hodgkin lymphoma (3 papers, 2021 to 2025). Distinct from Hodgkin lymphoma both morphologically and biologically, non-Hodgkin lymphoma (NHL) is characterized by the absence of Reed-Sternberg cells, can occur at any age, and usually presents as a localized or generalized lymphadenopathy associated with fever and weight loss. "CTSS inhibition caused antigen diversification in non-Hodgkin lymphoma that switched immunity by promoting CD8+ T cell polyclonal expansion and suppressing CD4+ T cells." (PMID 40707961, 2025). "Futher study revealed that it could enhanced the anti-tumor immune responses in Non-Hodgkin Lymphoma by inhibiting CTSS." (PMID 34266404, 2021).